TSHZ3 (teashirt zinc finger homeobox 3)
Diseases named in the same sentence as TSHZ3 in open-access papers:
TSHZ3 is named in the same sentence as 47 diseases in open-access papers, as found by Europe PMC text mining. Sharing a sentence is not in itself a finding about the gene and the disease. The quoted sentences say what the papers report.
autism spectrum disorder (5 papers, 2018 to 2024). A spectrum of developmental disorders that includes autism, and Asperger syndrome. "We previously linked TSHZ3 haploinsufficiency to autism spectrum disorder (ASD) and showed that embryonic or postnatal Tshz3 deletion in mice results in behavioral traits relevant to the two core domains of ASD, namely social interaction deficits and repetitive behaviors." (PMID 35292625, 2022). "Extrarenal anomalies in Tshz3-mutant mice include autism spectrum disorder (ASD)-like behavioral deficits and abnormal central respiratory rhythm generation." (PMID 39420202, 2024). "In addition, TSHZ3 controls breathing and has been identified as a critical region of the heterozygous deletions at 19q12-q13.11, in development of autism spectrum disorder symptoms." (PMID 34012728, 2021). "We linked heterozygous deletion of TSHZ3/Tshz3 gene to autism spectrum disorder (ASD) and used Camk2a-Cre mice to investigate the postnatal function of Tshz3, which is expressed by CPNs but not MSNs." (PMID 34349780, 2021).
prostate carcinoma (5 papers, 2011 to 2023). A carcinoma that arises from epithelial cells of the prostate gland. "The TSHZ3 gene promoter wasfound to be methylated in all the breast/prostate cancer cell lines and someof the breast cancer clinical specimens analyzed." (PMID 21423795, 2011). "TSHZ3 promoter methylation was found in breast and prostate cancer cells." (PMID 36966276, 2023). "The expression of “TSHZ3” is known to be downregulated in prostate cancer." (PMID 28148240, 2017).
autism (4 papers, 2020 to 2025). Persistent deficits in social interaction and communication and interaction as well as a markedly restricted repertoire of activity and interest as well as repetitive patterns of behavior. "For instance, we show that the Tshz3 gene associated with autism, known to be expressed in CPNs, is also expressed in SCINs." (PMID 34349780, 2021). "Loss of Tshz3 in cortical projection neurons is associated with autism phenotypes." (PMID 41081550, 2025).
breast carcinoma (2 papers, 2011 to 2012). "Given that the TSHZ3 gene promoter is reported to be frequently methylated in primary breast cancers and breast cancer cell lines, this gene has been suggested to display tumour suppressor function." (PMID 22433433, 2012). "Silencing of CCNE1, PLEKHF1, POP4, ZNF536 and TSHZ3 expression selectively reduced cell viability in cancer cells harbouring 19q12 gene amplification but had a significantly lower impact on the survival of breast cancer cells lacking amplification of this locus (t-test P < 0.05)." (PMID 22433433, 2012).
colorectal cancer (2 papers, 2022 to 2025). A primary or metastatic malignant neoplasm that affects the colon or rectum. "TSHZ3 has been shown to be downregulated in breast, prostate, and colorectal cancers, similar to our results." (PMID 34791179, 2022).
head and neck squamous cell carcinoma (2 papers, 2021 to 2025). A squamous cell carcinoma that arises from any of the following anatomic sites: lip and oral cavity, nasal cavity, paranasal sinuses, pharynx, larynx, and salivary glands. "The analysis revealed that TSHZ3 transcriptional levels were lower in nine cancer types, including LUAD, but higher in cholangiocarcinoma (CHOL) and head and neck squamous cell carcinoma (HNSC) compared with the normal tissues." (PMID 40264773, 2025).
hydronephrosis (2 papers, 2024 to 2025). Collection of urine in the renal pelvis that results in dilatation of the renal pelvis and calyces. "Variants in the human TSHZ3 gene, on the other hand, have not only been proved to cause MCDK but also to be associated with a higher rate of hydronephrosis and hydroureter." (PMID 41107504, 2025). "Our results provide evidence that heterozygous TSHZ3 variants are associated with human CAKUT, particularly MCDK, hydronephrosis, and hydroureter, and, inconsistently, with specific extrarenal features, including genital anomalies." (PMID 39420202, 2024). "Overlapping with the phenotype in Tshz3-mutant mice, we observed hydronephrosis, hydroureter, ureteropelvic junction obstruction, and MCDK (significantly) more frequently in heterozygous TSHZ3 variant carriers versus non-carriers in our CAKUT cohort." (PMID 39420202, 2024). "In line with the CAKUT phenotype observed in both siblings, MCDK but also hydronephrosis and hydroureter were more commonly observed in patients with versus without TSHZ3 variants, defining quite a specific CAKUT phenotype spectrum for TSHZ3 variant carriers." (PMID 39420202, 2024). "Similarly, only 5–27% of heterozygous Tshz3-mutant mice present with a hydronephrosis/proximal hydroureter phenotype, and only 5 of 14 (36%) patients with 19q12-q13.11 deletions including the TSHZ3 locus are affected by CAKUT." (PMID 39420202, 2024). "The similarity in TSHZ3 and DACT1 expression in the kidney and ureter is paralleled by a comparable CAKUT phenotype in carriers of TSHZ3 and DACT1 variants, i.e., MCDK or cystic kidney dysplasia, hydronephrosis and/or hydroureter." (PMID 39420202, 2024). "In addition, genital anomalies or CAKUT, including small echogenic kidneys, hydronephrosis, and hydroureter, were noted in two or five patients, respectively, with 19q12-q13.11 deletions encompassing TSHZ3." (PMID 39420202, 2024). "As genital anomalies and developmental delay were significantly more frequent in CAKUT patients with versus without rare TSHZ3 variants, observing combined hydronephrosis/-ureter, genital anomalies and cognitive impairment in patients is suggestive of a TSHZ3 aberration." (PMID 39420202, 2024). "A literature search of publications reporting patients with heterozygous deletions at 19q12-q13.1 encompassing the TSHZ3 locus revealed CAKUT phenotypes in 5/14 cases, i.e., hydronephrosis in 2/5 cases, small echogenic kidneys, hydroureter, or VUR grade II in 1/5 cases each." (PMID 39420202, 2024).
Hydroureter (2 papers, 2024 to 2025). The distention of the ureter with urine. "Heterozygous Tshz3-mutant mice show decreased viability and unilateral hydroureter in 5–27% of cases." (PMID 39420202, 2024).
Intellectual disability (2 papers, 2022 to 2024). "Using exome sequencing, we identified a heterozygous frameshift variant c.119_120dup p.Pro41SerfsTer79 in TSHZ3 in a 7-year-old girl with intellectual disability, behavioural issues, pyelocaliceal dilatation, and mild urethral stenosis." (PMID 36553458, 2022). "Heterozygous deletions at 19q12-q13.11 affecting TSHZ3, the teashirt zinc finger homeobox 3, have been associated with intellectual disability and behavioural issues, congenital anomalies of the kidney and urinary tract (CAKUT), and postnatal growth retardation in humans and mice." (PMID 36553458, 2022). "Overlapping phenotypes in CAKUT patients with TSHZ3 missense variants and patients with deletions of 19q12-q13.11 encompassing TSHZ3 thus include developmental delay, intellectual disability, genital anomalies, and CAKUT." (PMID 39420202, 2024). "In 14 patients with 19q12-q13.11 deletions including TSHZ3, the characteristic features were feeding difficulty, developmental delay including speech delay, cognitive impairment or intellectual disability, and autistic behavior." (PMID 39420202, 2024).
lung adenocarcinoma (2 papers, 2019 to 2025). A carcinoma that arises from the lung and is characterized by the presence of malignant glandular epithelial cells. "However, analyzing the maximal common subgraph of the two networks revealed clues about common downstream effects of these genes and a potential insight into TSHZ3’s contribution to lung adenocarcinoma biology." (PMID 31253832, 2019).
lung carcinoma (2 papers, 2019 to 2025). "We evaluated the prognostic potential of TSHZ3 in lung cancers by generating survival curves using the Kaplan–Meier plotter." (PMID 40264773, 2025). "First, we explored prognostic data and predicted the function of TSHZ3 in lung cancer through bioinformatics analysis." (PMID 40264773, 2025). "The results suggested that high TSHZ3 expression levels were correlated with a favorable prognosis of overall survival (OS) in lung cancer (OS: hazards ratio (HR) = 0.73, 95% confidence intervals (CI) = 0.62 to 0.86, p = 0.00023) and LUAD (HR = 0.66, 95% CI = 0.52 to 0.85, p =0.0012)." (PMID 40264773, 2025).
ovarian carcinoma (2 papers, 2012 to 2021). A malignant neoplasm originating from the surface ovarian epithelium. "Additional work is warranted to clarify mechanisms of deregulation and the role of TSHZ3 in ovarian cancer." (PMID 22514011, 2012). "In addition, the downregulation or deletion of TSHZ3 function is involved in the pathogenesis of ovarian cancer, which suggests that TSHZ3 plays an oncogenic role." (PMID 34368227, 2021). "TSHZ3 was identified as a target of recurrent breakage in ovarian cancer." (PMID 22514011, 2012). "Additionally, Affymetrix SNP 6.0 data obtained from the TCGA ovarian cancer study was also evaluated for independent breakpoints affecting TSHZ3 in the absence of CCNE1 amplification." (PMID 22514011, 2012).
apneic episodes (1 paper, 2023).
breast tumor (1 paper, 2011). "We also examined 7 additional breast tumor tissues, andfound that several had some degree of methylation at the TSHZ3 gene promoter regionanalyzed." (PMID 21423795, 2011).
cryptorchidism (1 paper, 2024). The failure of one or both testes of a male fetus to descend from the abdomen into the scrotum during the late part of pregnancy. "The genital anomalies recurrently observed in TSHZ3 variant carriers were cryptorchidism and phimosis." (PMID 39420202, 2024).
developmental delay (1 paper, 2024). "Specific extrarenal features, i.e., genital anomalies and developmental delay, were significantly more frequent in patients with versus without TSHZ3 variants." (PMID 39420202, 2024). "Among these features, genital anomalies and developmental delay were significantly more frequent in CAKUT patients with versus without rare TSHZ3 variants (5/12 (42%) versus 44/291 (15%), p = 0.029, and 3/12 (25%) versus 17/291 (6%), p = 0.037, respectively, two-tailed Fisher’s exact test)." (PMID 39420202, 2024).
glioblastoma (1 paper, 2021). The most malignant astrocytic tumor (WHO grade IV). "The expression of TSHZ3 is significantly downregulated in human glioma tissues and cell lines, and overexpression of TSHZ3 decreases the invasiveness of U87 and U251 glioblastoma cells." (PMID 34368227, 2021).
Horseshoe kidney (1 paper, 2024). A connection of the right and left kidney by an isthmus of functioning renal parenchyma or fibrous tissue that crosses the midline. "The other anomalies in TSHZ3 variant carriers, i.e., kidney (hypo)dysplasia, VUR, ureteropelvic junction obstruction, duplex kidney, posterior urethral valves, kidney cysts/cystic kidney dysplasia, and horseshoe kidney, were not present significantly more frequently than in non-carriers." (PMID 39420202, 2024).
malignant glioma (1 paper, 2016). A grade III or grade IV glioma arising from the central nervous system. "Other key factors that became apparent from these GRNs include TSHZ3, previously reported to correspond to a novel potential tumor suppressor, and LHX9, which is aberrantly methylated and downregulated in malignant gliomas of childhood." (PMID 27198694, 2016).
multicystic dysplastic kidney (1 paper, 2024). Multicystic dysplastic kidney (MCDK) is a congenital anomaly of the kidney and urinary tract (CAKUT) in which one or both kidneys (unilateral or bilateral MCDK respectively) are large, distended by multiple cysts, and non-functional. "In whole-exome sequencing data of two siblings with genetically unresolved multicystic dysplastic kidneys (MCDK), prioritizing variants in murine CAKUT-associated genes yielded a rare variant in the teashirt zinc finger homeobox 3 (TSHZ3) gene." (PMID 39420202, 2024).
non-small cell lung carcinoma (1 paper, 2021). A group of at least three distinct histological types of lung cancer, including non-small cell squamous cell carcinoma, adenocarcinoma, and large cell carcinoma.
tumor (11 papers, 2010 to 2025). "In both AOCS and TCGA 1 cohorts, high TSHZ3 expression was associated with the C1 molecular subtype, which is characterized by intense tumour stromal and epithelial–mesenchymal transition gene expression signatures and poor clinical outcome." (PMID 22514011, 2012). "This cluster was enriched in genes involved in differentiation and developmental processes (for example, SOX1 and SOX9, HOXD3 and HOXD8, and TBX4) and genes implicated as tumor suppressors (for example, SOX1 and SOX17, TSHZ3, WT1-AS, and FGF14)." (PMID 40931149, 2025). "TSHZ2 and TSHZ3 genes turned out to be the most interesting candidates fornovel tumor suppressor genes." (PMID 21423795, 2011). "TSHZ3 functions as a tumor suppressor by inhibiting cancer cell invasion in brain glioma." (PMID 40264773, 2025). "It indicated that TSHZ3 may act as a tumor suppressor gene in LUAD." (PMID 40264773, 2025). "As a potential tumor suppressor, TSHZ3 may influence the prognosis of patients with LUAD." (PMID 40264773, 2025). "Therefore, we assessed its role in LUAD prognosis and found that high TSHZ3 expression predicts a favorable outcome, reinforcing our hypothesis that TSHZ3 acts as a tumor suppressor in this cancer." (PMID 40264773, 2025). "However, most studies thus far have focused on TSHZ3 25, with only sporadic reports available concerning TSHZ1 and TSHZ2 in non-neoplastic diseases." (PMID 33850468, 2021).
cancer (8 papers, 2011 to 2025). A tumor composed of atypical neoplastic, often pleomorphic cells that invade other tissues. "Teashirt zinc finger homeobox 3 (TSHZ3) is a transcription factor implicated in the progression of certain cancers." (PMID 40264773, 2025). "GO and pathway analyses suggested that TSHZ3 is involved in immune responses and various cancer-related processes." (PMID 40264773, 2025). "Consistent with this hypothesis, we observed that cancer cells harbouring 19q12 amplification require the expression of not only CCNE1, but also PLEKHF1, POP4 and TSHZ3 for their survival." (PMID 22433433, 2012). "Therefore, we anticipated that the TSHZ2 and TSHZ3 promotersmight be hypermethylated in the non-expressor cancer cell line cells whereas in theexpressors they would be hypomethylated, as it has been demonstrated with othertumor suppressor genes." (PMID 21423795, 2011).
neurodevelopmental disorder (2 papers, 2020 to 2022). A behavioral and cognitive disorder with onset during the developmental period that involves impaired or aberrant development of intellectual, motor, or social functions. "This confirms TSHZ3 as a novel disease gene for neurodevelopmental disorder in combination with behavioural issues and CAKUT." (PMID 36553458, 2022). "Altogether, this could suggest a role of TSHZ3 in cortical development and in the pathogenesis of neurodevelopmental disorders." (PMID 32999390, 2020).
psychiatric disorder (1 paper, 2024). A disorder characterized by behavioral and/or psychological abnormalities, often accompanied by physical symptoms. "In psychiatric disorders, ZNF537/TSHZ3 and ZNF536 were expressed in the cerebral cortex, and supported by CRISPR information." (PMID 38720348, 2024).
TSHZ3 also shares sentences with these, for which no sentence is quoted: alcohol dependence (1 paper); Central hypothyroidism (1); cholangiocarcinoma (1); Cognitive impairment (1); glioma (1); hypogonadism (1); Kidney Cyst (1); leukoplakia (1); liver cancer (1); lung squamous cell carcinoma (1); nasopharyngeal carcinoma (1); neuropathies (1); phimosis (1); prostate adenocarcinoma (1); Renal Disorder (1); serous ovarian carcinomas (1); speech delay (1); thyroid (1); thyroid disorder (1); triple-negative breast carcinoma (1); type 1 diabetes (1); type 2 diabetes (1).